MYC (MYC proto-oncogene, bHLH transcription factor)
Diseases named in the same sentence as MYC in open-access papers (continued):
Sharing a sentence is not in itself a finding about the gene and the disease.
tumor (continued). "Oncogenic signalling pathways such as PI3K/AKT, MAPK, and MYC affect constitutive PD-L1 expression, while pro-inflammatory cytokines, particularly interferon-gamma (IFN-γ) produced by tumour-infiltrating lymphocytes (TILs), induce adaptive PD-L1 expression." (PMID 41284319, 2025). "We found that MYC, E2F1, and EIF4E are all positively correlated with PRMT5 and KRAS with an R-value > 0.70 and a p-value < 0.01 in CRC patient tumor samples." (PMID 40864819, 2025). "The role of eccDNA in cancer has been extensively documented, especially its function in amplifying oncogenes such as MYC and EGFR, which contributes to tumor heterogeneity and drug resistance 37,66,187." (PMID 40521196, 2025). "In contrast, tumor promoters such as MYBL2, TYMS, MYC, MCM7, and EGFL7 were downregulated in EF-24–treated cells." (PMID 40986633, 2025). "In SyS, the interplay between MYC and receptor tyrosine kinases (RTKs), such as PDGFR and VEGFR, plays a critical role in tumor progression, highlighting a complex relationship that drives oncogenesis." (PMID 40076599, 2025). "By regulating acetylation with interactions involving MYC, AKT, and TGF-β, P300 drives epigenetic changes that promote tumor growth and progression." (PMID 39979245, 2025). "The transformed tumor expressing CD10, BCL2, BCL6, and MYC with high Ki-67 (~70%) is consistent with double-expressor or double-hit DLBCL, associated with rapid proliferation and transformation from FL." (PMID 41146768, 2025). "Tumor-specific deep crypt secretory (tDCS, cluster 10) cells were enriched for apical junction, apoptosis, EMT, MYC signaling, and E2F targets, reflecting secretory lineage reprogramming and stress-associated differentiation." (PMID 41282138, 2025). "The inhibition of BCL6 or mTOR can reverse the resistance of tumor cells.In addition, the activation of the MAPK signaling pathway, c – MYC, etc., also contributes to the induction of tumor resistance." (PMID 39838405, 2025). "Significantly enriched terms for SQ are E2F and MYC targets, hypoxia and oestrogen response and for NET tumours, neuroepithelial cell differentiation and GABAergic signalling." (PMID 39995112, 2025). "By contrast, in the Met group, TFs related to tumor angiogenesis, metastasis and EMT, such as XRCC4, MYC and MAZ showed elevated activity 23–25." (PMID 41413734, 2025). "Western blotting analysis of tumor tissues found that EVO remarkably reduced the expression levels of proteins β-catenin, c-MYC, Cyclin D1, and ASS1 in subcutaneous CRC syngeneic tumor allografts." (PMID 41304979, 2025). "WWOX inhibits MYC activity by binding to MYC on chromatin, mitigating MYC’s suppression of miR-146a, which in turn inhibits fibronectin expression, EMT, tumor invasion, and metastasis." (PMID 41228229, 2025). "The master transcriptional factors of MES state cells, such as c-MYC, PRRX1 and NOTCH1 were highly upregulated in the resistant tumor cells, together with the SCP marker S100B and stem cell markers KIT and SALL4." (PMID 40962798, 2025). "The stemness genes highly expressed in the C0 subtype included CTNNB1, CD44, and KDM5B, while in the Normal tissue adjacent to neoplasm group, CTNNB1, CD44, and MYC were highly expressed." (PMID 40616092, 2025). "In colitis-associated cancer (CAC), inflammation and DNA methylation-dependent down-regulation of miR-34b-5p mediate c-MYC expression and CRL4DCAF4 E3 ligase activity, promoting tumor development." (PMID 40230836, 2025). "In fact, the expression levels of EGFR, MYC, CDK4, and MDM2 genes commonly carried by ecDNA rank in the top 1% of tumor genomes." (PMID 41030947, 2025). "Among the key genes affected in DLBCL are MYC, SLIT2, KLF4, and CDKN2A, whose inactivation facilitates uncontrolled proliferation and tumor progression." (PMID 40943058, 2025). "MYC upregulates 3-hydroxy-3-methyl-glutaryl coenzyme A reductase (HMGCR), the rate-limiting enzyme in cholesterol biosynthesis, further enhancing tumor cell proliferation and survival." (PMID 41281744, 2025).
tumor (continued). "Here we present new humanized isogenic models for G3MB driven by MYC amplification and overexpression of TGFβ pathway effectors ACVR2A, TGFβR1, and TGFβ1 that recapitulate the human tumor type." (PMID 41415380, 2025). "The let-7 family mainly acts as tumor suppressors by targeting oncogenes like RAS and MYC and controlling the cell cycle." (PMID 41514860, 2025). "MYC EIS positively correlated with MYC mRNA expression and tumor purity estimation but negatively correlated with leukocyte fraction estimation." (PMID 40355593, 2025). "KIMAT1 promotes MYC transcription by activating mTOR; together with LDHB, it enhances glycolysis and the TCA cycle, thereby promoting tumor growth." (PMID 40746614, 2025). "They display a more nuclear accumulation of β-catenin and high expression of MYC, as well as distinctiveness of mucin 5 (MUC5) expression, indicating the specific features of a morphologically distinct tumor." (PMID 40943367, 2025). "In double-hit lymphomas, combined dysregulation of MYC and BCL2 (often with BCL6) results in synergistic oncogenesis, characterized by rapid tumor growth and resistance to apoptosis." (PMID 41010038, 2025). "Among them, seven cancer genes (ERBB2, ERBB3, PPARG, MYC, CCND1, CCNE1, MDM2) were detected to be amplified in both ctDNA and tumor tissues, indicating the reliability of ctDNA in reflecting the genomic features of tumors." (PMID 40191434, 2025). "We identified a primary tumour sample with two distinct subclones (MB272), harbouring MYC (C3) and MYCN (C2) amplifications simultaneously." (PMID 40335697, 2025). "While the precise contribution of these metabolic changes to accelerated tumor growth remains to be fully elucidated, a shift in the MITF/MYC balance provides additional insight." (PMID 40558540, 2025). "This network can upregulate MYC and BCL2, restore PTEN expression, and intervene in the PI3K/AKT pathway, affecting tumor cell proliferation and chemoresistance." (PMID 40703518, 2025). "The standard double-color FISH tests confirmed that all tumor cells had translocations involving IGH/BCL2 and IGH/MYC, along with a BCL6 gene rearrangement." (PMID 41142614, 2025). "MYC activates the transcription of telomerase (TERT), which sustains the proliferation of tumor cells." (PMID 40290126, 2025). "The dephosphorylation of c-MYC at T58 by PP2A-B56α and at S62 by PP2A-B55α represents a critical regulatory switch, with the former promoting tumor-suppressive degradation and the latter enabling tumorigenic stabilization and transcriptional activation." (PMID 41146310, 2025). "In vivo, NCL inhibited CD8+ T cell glucose metabolism through the MYC/TXNIP axis, hindering anti-tumor immune function." (PMID 40346484, 2025). "Studies have shown that MYC amplification activates signaling pathways such as RAS/MAPK and PI3K/AKT, enhancing tumor cell motility and invasiveness." (PMID 41189895, 2025). "One recent study highlighted lipid-based nanoparticles delivering MYC-targeted siRNAs (such as DCR-MYC) into tumor cells, leading to efficient MYC silencing, potent anti-proliferative effects, and notable reduction of tumor burden in preclinical models." (PMID 40365020, 2025). "Follow-up research confirmed an increased promoter methylation in key tumor suppressor genes such as MYC and SLIT2, likely leading to reduced gene expression and contributing to tumor growth." (PMID 40299416, 2025).
tumor (continued). "In non-small cell lung cancer, hnRNPH1, regulated by MYC, mediates a splicing switch of KHK pre-mRNA from the KHK-C to the KHK-A isoform, promoting metabolic reprogramming to support tumor growth." (PMID 40507967, 2025). "PDE4B is reported to be able to promote immune infiltration of the tumor microenvironment (TME) and increase the clonal formation, proliferation, migration, and invasion of gastric cancer via the PI3K/AKT/MYC pathway." (PMID 41179677, 2025). "Studies suggest that MYC indirectly enhances ITGAV-mediated pathways, contributing to the establishment of pre-metastatic niches and supporting the survival of circulating tumor cells." (PMID 40076599, 2025). "Since MYC and KRAS-mediated signaling is frequently deregulated in HGSOC, we generated a tumor model by oncogenic transformation of iFTSECs, which constitute the origin of HGSOC." (PMID 40550880, 2025). "Nevertheless, our sequencing protocol on FFPE tissue allowed us to classify the tumor as ATRT, MYC subgroup, resulting in the initiation of appropriate chemotherapy." (PMID 41180011, 2025). "In MYC-induced lymphoma mice, DNMT3B hypomorphism increased cell proliferation and accelerated tumor growth by up-regulating the expression of tumor modifier genes." (PMID 40115961, 2025). "The transgenic HCC mouse models, MYC/LT2 mice, show clear attenuation of tumor development via AAV‐mediated miR‐20a‐Tough‐Decoy treatment." (PMID 40536197, 2025). "Coactivation of KRAS and MYC enhances the secretion of tumor-derived CCL9 and IL-23, driving stromal reprogramming, promoting angiogenesis, and excluding tumor-infiltrating T, B, and NK cells." (PMID 40813760, 2025). "This process facilitates the production of oncogenic proteins like HIF1α, MYC, VEGFA and BCL-2, which support tumour growth, angiogenesis and cell survival." (PMID 40849356, 2025). "This increase was further accompanied by upregulation of MYC targets V1 pathway (estimate = 0.034, FDR = 2.1 × 10-25), indicating accelerated tumor growth and an inadequate therapeutic response." (PMID 41392193, 2025). "PLK1 expression can promote MYC to activate Hedgehog signaling pathway by degrading PDCD4, and then promote the proliferation of tumor cells." (PMID 40612941, 2025). "Given our prior findings implicating CMSP in the regulation of the JAK2/STAT3/c-Myc axis, we further focused on MYC as a potential effector mediating the anti-tumor effects of CMSP." (PMID 41347093, 2025). "They selectively block MYC-mediated transcriptional activation by stabilizing the global repressor of MYC proteins, MIZ, in a tumor cell-specific manner." (PMID 39851497, 2025). "Together, these independent cases suggest the possibility that MYC and MYCN amplifications co-occur within the same tumour more frequently than originally thought." (PMID 40335697, 2025). "TEAD4, TBP, MYC, and ELF5 constituted the transcription factor regulatory network of C2 CPE+ tumor cells." (PMID 40230840, 2025). "Inflammation and DNA methylation-dependent downregulation of miR-34b-5p mediates c-MYC expression and CRL4DCAF4 E3 ligase activity, promoting tumor development." (PMID 40230836, 2025). "FTO exerts oncogenic effects on various types of cancer cells, promoting tumor cell growth by activating survival and cell-cycle signaling, such as PI3K/Akt/mTOR pathway, MYC, β-catenin, and CEBPA." (PMID 40234389, 2025). "KC2 tumours showed significantly reduced levels of P16INK4A and increased levels of c‐MYC, consistent with their high proliferative capacity and aggressive clinical behaviour." (PMID 41025426, 2025). "By regulating pathways such as IFN-α, MYC, E2F, and ATP production, NR2E3 emerges as a versatile tumor suppressor with broad implications in cancer biology." (PMID 39809731, 2025).
tumor (continued). "In other malignancies, MYC and MET have been shown to cooperate to drive tumorigenesis, and their co-overexpression tends to exacerbate tumor growth and patient prognosis." (PMID 39858062, 2025). "In conclusion, our results demonstrate that RPL35A binds to MYC via its 2 to 22 amino acid residues, thereby facilitating MYC-dependent SKP2 transcription, enhancing glycolysis, and promoting tumor progression." (PMID 41241099, 2025). "Using immunohistochemistry, we identified another case in which both MYC and MYCN staining were seen in the same tumour sample." (PMID 40335697, 2025). "Tryptophan metabolite Indole‐3‐aldehyde (I3A) downregulates cytosolic AhR and p‐ERK/c‐MYC proteins, together enhancing STAT3 phosphorylation and tumor immunogenicity." (PMID 40583248, 2025). "In lung adenocarcinoma (LUAD), METTL3 triggers the oncogenic molecule c-MYC by enhancing the stability of lncRNA LCAT3, interacting with the upstream protein FUBP1, and promoting tumor cell growth, infiltration, and dissemination." (PMID 40271153, 2025). "In BC, the genes STAT3, CTNNB1, and MYC were upregulated, while TNF was downregulated in tumor tissues." (PMID 41186627, 2025). "A molecular characteristic of such cells is that they require HDAC10 to maintain the expression of MYC and POLD1 (i.e., HDAC10ness in analogy to the BRCAness of certain tumor cells)." (PMID 40301616, 2025). "The let-7 family primarily functions as a tumor suppressor by targeting oncogenes such as RAS and MYC." (PMID 41514860, 2025). "In cancer, eccDNA often carries oncogenes such as MYC, EGFR, and CDK4, enabling their overexpression and contributing to tumor progression 20,63,160." (PMID 40521196, 2025). "Our data support that in MP‐subtype LUAD, recruited M2‐like macrophages stimulate tumor cell FOSL2 expression through secreting TGFβ, thereby increasing accessibility to novel MYC chromatin binding sites." (PMID 39899538, 2025). "Conversely, elevated levels of MYC diminishes the AR transcriptional program in pre-clinical models and CRPC tumours, at least in part by disrupting transcriptional pause release at AR target genes." (PMID 40163908, 2025). "Up-regulation of fatty acid oxidation (FAO) intermediates is observed in MYC overexpressed TNBC, and inhibition of FAO can reduce energy metabolism and repress tumor growth of this TNBC tumor subtype." (PMID 41444950, 2025). "The MYC and MYCN subclones in this tumour sample had proliferating and differentiating compartments." (PMID 40335697, 2025). "Inhibiting FAO decreases energy metabolism in MYC-overexpressing TNBC cells and inhibits tumor growth in a patient-derived xenograft (PDX) model." (PMID 39402211, 2025). "Simultaneously, MYC represses pro-apoptotic factors and promotes the expression of anti-apoptotic proteins such as BCL-2, enabling tumor cells to survive under stress conditions, including hypoxia and treatment-induced DNA damage." (PMID 40076599, 2025). "The small molecule drug NHWD-870 is released to target MYC therapy and inhibit the production of downstream cytokines CCL2 and IL13, promoting the polarization of tumorigenic M2 macrophages to anti-tumor M1 macrophages." (PMID 39897587, 2025). "Other potential limitations include assessing for pLoF in oncogenic candidates such as RET, ROS1, FGFR4, and MYC, while FAT1 and LEF1 reported to oscillate between oncogenic and tumour suppressive behaviour." (PMID 41038821, 2025).
tumor (continued). "Conversely, suppression of MYC activity leads to a decline in TERC levels, subsequently inhibiting tumor cell proliferation and suppressing tumor progression." (PMID 39871386, 2025). "Our and others' scRNA-seq data 17 showed that around 30% of TECs are enriched in MYC and this proliferating TEC subset appears to give rise to most, if not all, other TEC subsets, functioning as the Achilles' heel of the tumor vascular system." (PMID 40303332, 2025). "Overall, increased apoptotic response and decreased MYC expression highlight AZD5153 and pazopanib as an effective drug combination in mitigating DDLPS progression in vivo, with significant tumor suppressive activity compared to either drug alone." (PMID 40121334, 2025). "MYC regulates genes involved in glucose uptake (GLUT1) and glycolysis (HK2, PFK1), enhancing the glycolytic capacity of tumor cells." (PMID 41281744, 2025). "The combined treatment strongly impaired the translation of oncogenic proteins, such as MYC and MCL-1, and increased their proteasome-dependent degradation, thus favouring tumour cell death." (PMID 39533070, 2025). "The oncogenic transcription factors MYC and HIF-1α critically regulate cellular metabolism in cancer by driving metabolic reprogramming that supports tumor growth and survival." (PMID 40707487, 2025). "Conversely, upregulation of 8q24 containing MYC was evident in proliferative, immunoreactive, mixed STICs, and HGSC, supporting its role in tumor progression." (PMID 40667280, 2025). "We therefore nominate the CoA biosynthetic pathway as a metabolic vulnerability in PDGF/VEGF- and MYC-driven tumors, proposing that inhibition of CoA biosynthesis, alone or in combination with anti-angiogenic regimens, may help restrict metabolic adaptation and impede tumor progression." (PMID 40832336, 2025). "In CRC, both WNT and MYC signaling pathways are essential for CSC maintenance, with their interplay supporting CSC survival and tumor progression." (PMID 40661135, 2025). "In MYC-induced lymphoma mice, conditional knock down of DNMT3B increased cell proliferation and accelerated tumor growth by up-regulating the expression of tumor modifier genes." (PMID 40115961, 2025). "The MYC oncogene is a well-documented driver of tumorigenesis in many cancers, and the type-1 interferon pathway is an important pathway in the antiviral response; however, their roles in the formation of the tumor immunosuppressive microenvironment remain unclear." (PMID 39751650, 2025). "MYC, FOXA1, HIF1A, PAM50 and both ROR are determined at the gene expression level in RNA extracted from FFPE tumor tissue using the nCounter platform." (PMID 40997111, 2025). "In Vivo administration of AAV‐miR‐342‐3p attenuates tumor development and prolongs the survival of LT2/MYC and LT2/RAS mice." (PMID 40536197, 2025). "To explore the clinical and immunological relevance of MYC expression in OSCC, we utilized the TIMER2.0 database to assess its correlation with tumor-infiltrating immune cells." (PMID 41347093, 2025). "The tSNE score was positively associated with immune- and inflammation-related pathways (e.g., interferon and interleukin signaling), as well as tumor progression and metastasis pathways (e.g., TGF-β, MYC, E2F, and EMT)." (PMID 40438104, 2025). "Ubiquitin-mediated degradation of MYC diminishes its binding to the ENO1 promoter, thereby reducing ENO1 transcription and suppressing glycolysis in tumor cells." (PMID 39980052, 2025).